PPIB (peptidylprolyl isomerase B)
Description:
Peptidyl-prolyl cis-trans isomerase that catalyzes the cis-trans isomerization of proline imidic peptide bonds in oligopeptides and may therefore assist protein folding.
Synonyms: SCYLP; CYPB; OI9; PPIase; B; CYP-S1; HEL-S-39
Tractability: Small molecule: a structure with a bound ligand is known; a high-quality ligand is known; it belongs to a druggable protein family. Antibody: UniProt predicts a signal peptide or a membrane-spanning region. PROTAC: ubiquitination databases record sites on it; its protein half-life has been measured; a small molecule that binds it is known.
Target class: Isomerase; Enzyme
Gene: Protein-coding gene on chromosome 15 (64,155,740 to 64,163,159, reverse strand). Ensembl gene ENSG00000166794.
Subcellular location: Virion; Endoplasmic reticulum lumen; Melanosome
Subcellular location (Human Protein Atlas): Endoplasmic reticulum; Nucleoplasm; Predicted to be secreted
Pathways (Reactome):
Disease: SARS-CoV-1 activates/modulates innate immune responses
Extracellular matrix organization: Collagen biosynthesis and modifying enzymes
Gene Ontology:
Molecular function: peptidyl-prolyl cis-trans isomerase activity; protein binding; RNA binding; RNA polymerase binding; collagen binding; cyclosporin A binding
Biological process: bone development; host-mediated activation of viral genome replication; host-mediated activation of viral process; neutrophil chemotaxis; positive regulation of multicellular organism growth; protein folding; protein stabilization; regulation of post-translational protein modification
Cellular component: endoplasmic reticulum; extracellular exosome; focal adhesion; melanosome; membrane; nucleus; perinuclear region of cytoplasm; cytosol; endoplasmic reticulum lumen; protein-containing complex; endoplasmic reticulum chaperone complex; smooth endoplasmic reticulum
Genetic constraint (gnomAD): Loss-of-function variants: 15 observed, 20.93 expected, observed/expected ratio (o/e) 0.72, 90% interval 0.48 to 1.1. The upper end of that interval is the gene's LOEUF score, 1.1, which puts it in group 4 of 6, group 1 being the genes least tolerant of losing a copy. Missense variants: 278 observed, 299.73 expected, observed/expected ratio (o/e) 0.93, 90% interval 0.84 to 1.02. Synonymous variants: 129 observed, 117.83 expected, observed/expected ratio (o/e) 1.09, 90% interval 0.95 to 1.27.
Homologues: Orthologues: macaque PPIB (100% identical), chimpanzee PPIB (99% identical), guinea pig PPIB (98% identical), dog PPIB (96% identical), mouse Ppib (94% identical), pig PPIB (94% identical), rat Ppib (94% identical), rabbit PPIB (87% identical), zebrafish ppib (78% identical), tropical clawed frog ppib (76% identical), Caenorhabditis elegans cyn-9 (39% identical), Drosophila melanogaster Cyp40 (38% identical). Paralogues in human: PPIC (63% identical), PPIA (50% identical), PPIF (50% identical), PPIE (49% identical), PPID (48% identical), PPIAL4C (44% identical), PPIH (44% identical), PPIAL4A (43% identical), PPIAL4D (43% identical), PPIAL4E (43% identical), PPIAL4F (43% identical), PPIAL4G (42% identical), and 10 more.
Diseases named in the same sentence as PPIB in open-access papers:
PPIB is named in the same sentence as 355 diseases in open-access papers, as found by Europe PMC text mining. Sharing a sentence is not in itself a finding about the gene and the disease. The quoted sentences say what the papers report.
melanoma (46 papers, 2007 to 2026). A malignant, usually aggressive tumor composed of atypical, neoplastic melanocytes. "WM9 is a melanoma cell line that was transiently transfected with 20 nM and 50 nM siRNA against cyclophilin-B (PPIB), or a scrambled negative control siRNA." (PMID 23977142, 2013).
multiple myeloma (27 papers, 2013 to 2026). "While we, after multiple rounds of optimization, succeeded to achieve an acceptable and consistent knockdown efficiency for both FKBP11 and PPIB in the hybridoma cell line, we failed doing so for the plasma cell myeloma cell line JK-6L." (PMID 35456020, 2022).
diabetes (21 papers, 2013 to 2025). "A team lead by Seyed Hasnain at the Indian Institute of Technology Delhi identified an enzyme, PpiB, from M. tuberculosis that promoted biofilm formation and showed that PpiB interacts with several drugs that are currently used to treat diabetes, immunological diseases and cancer." (PMID 30675370, 2019).
breast carcinoma (16 papers, 2006 to 2025). "Increased apoptotic cell proportions and ERS-induced apoptosis independently promoted by PPIB in breast cancer cells were also observed." (PMID 38360722, 2024). "Considering the heterogeneous nature of ER+ breast cancer, we also tested if PPIB was upregulated in TAM-treated ER− cells." (PMID 38360722, 2024). "Real-time quantitative RT-PCR was carried out to measure uPA and PAI-1 mRNA expression between relapsed and non-relapsed breast cancers on the 87 samples studied using the cyclophilin B (PPIB) gene, known to be stably expressed in breast tissues, as an internal control." (PMID 16945123, 2006).
colorectal cancer (15 papers, 2014 to 2025). A primary or metastatic malignant neoplasm that affects the colon or rectum.
osteogenesis imperfecta (15 papers, 2009 to 2024). Osteogenesis imperfecta (OI) comprises a heterogeneous group of genetic disorders characterized by increased bone fragility, low bone mass, and susceptibility to bone fractures with variable severity. "Nonetheless, this mechanism is partly supported by genetic studies demonstrating reduced collagen type I crosslinking in PPIB-deficient mice, which also develop features of osteogenesis imperfecta." (PMID 38900587, 2024). "PPIB is also associated with pathological conditions potentially affecting osteoarthritis, such as osteogenesis imperfecta." (PMID 31809510, 2019). "Additionally, CypB has been presented as a key factor for the correct folding of collagen type I, and mutations in the CypB gene PPIB have been linked to the occurrence of Osteogenesis Imperfecta in humans." (PMID 31717385, 2019). "Mutations in CRTAP (coding for cartilage-associated protein), LEPRE1 (coding for prolyl 3-hydroxylase 1 [P3H1]) or PPIB (coding for Cyclophilin B [CYPB]) cause recessive forms of osteogenesis imperfecta and loss or decrease of type I collagen prolyl 3-hydroxylation." (PMID 20485499, 2010). "Osteogenesis imperfecta (OI) types VII, VIII and IX, caused by recessive mutations in cartilage-associated protein (CRTAP), prolyl-3-hydroxylase 1 (P3H1) and cyclophilin B (PPIB), respectively, are characterized by the synthesis of overmodified collagen." (PMID 31171565, 2019). "Interestingly, PPIB has been implicated in the rare skeletal disorder ‘osteogenesis imperfecta’ (OI), with a recent study reporting a rare pedigree with an autosomal recessive OI caused by two novel PPIB mutations." (PMID 35457215, 2022). "Notably, though excessive TGF-β1 signaling is a common mechanism in these mouse models of osteogenesis imperfecta, these mice do not develop organ fibrosis, consistent with the notion that PPIB may be required for TGF-β1 signaling to initiate the development of fibrosis." (PMID 38900587, 2024).
hepatocellular carcinoma (11 papers, 2014 to 2025). A malignant tumor that arises from hepatocytes. "PPIB is associated with malignant progression in gastric cancer, hepatocellular carcinoma, pancreatic cancer, and head and neck squamous cell cancer and is considered a candidate biomarker for these cancers." (PMID 37280525, 2023). "In cancer biology, PPIB is associated with malignant progression and regulation of genes involved in the pathogenesis of gastric cancer,hepatocellular carcinoma, pancreatic cancer and is considered as a candidate biomarker for these cancers." (PMID 34257533, 2021).
lymphoma (10 papers, 2013 to 2024). A malignant (clonal) proliferation of B- lymphocytes or T- lymphocytes which involves the lymph nodes, bone marrow and/or extranodal sites. "Second, using a chemical crosslinking approach in mouse lymphoma cell lines followed by mass spectrometry-based identification, PPIB was found to reside in a complex associated with unassembled, incompletely folded immunoglobulin heavy chains." (PMID 35456020, 2022).
liver cancer (8 papers, 2016 to 2024). An epithelial or non-epithelial malignant neoplasm that arises from the liver. "In this RNA ISH assay, peptidylprolyl isomerase B (PPIB), a protein highly expressed in liver cancer served as a positive control and dihydrodipicolinate reductase (dapB) as the negative control." (PMID 27618777, 2016).
Sepsis (7 papers, 2017 to 2025). Sepsis is defined as life-threatening organ dysfunction caused by a dysregulated host response to infection. "PpiB clearly plays an important role in infection, as a ppiB mutant is attenuated in abscess and sepsis models of infection, and displays reduced intracellular survival." (PMID 31208155, 2019).
neuroblastoma (6 papers, 2017 to 2024). Neuroblastoma (NB) is the most common solid, extracranial childhood tumor. "Together these findings strongly suggest that ACE2, CD147, PPIA, and PPIB are potential biomarkers and therapeutic targets for neuroblastoma." (PMID 38398114, 2024).
Hyperglycemia (5 papers, 2017 to 2025). An increased concentration of glucose in the blood. "We also report that expression of GAPDH and PPIB in PBMCs is affected by hyperglycaemia in T2DM patients making them unsuitable as references genes for measuring mRNA expression." (PMID 36627346, 2023).
tuberculosis (5 papers, 2014 to 2025). A chronic, recurrent infection caused by the bacterium Mycobacterium tuberculosis. "Future work is needed to test these medications against tuberculosis in humans, but given PpiB is found in different bacteria, there may be broader promise of using these repurposed drugs to combat other infections." (PMID 30675370, 2019).
prostate carcinoma (4 papers, 2019 to 2025). A carcinoma that arises from epithelial cells of the prostate gland. "GAPDH could enhance the transcriptional activity of AR in prostate cancer cells, and PPIB could regulate cell-cycle related genes including CCDC74A which further promotes cell proliferation." (PMID 37729607, 2023). "In vivo, an AOC targeting the TENB2 with siRNA targeting PPIB gene to target prostate cancer cells was dosed 24 mg/kg three times over 3 days by i.v administration into a mouse tumour model, and demonstrated around a 30% knockdown in expression of PPIB." (PMID 36678864, 2023).
renal fibrosis (3 papers, 2020 to 2024). A final common manifestation of a wide variety of chronic kidney diseases characterized by glomerulosclerosis and tubulointerstitial fibrosis. "By contrast, studies with the SfA-derived pancyclophilin inhibitor GS-642362, which targets PPIA, PPIB, and PPIF, in the unilateral ureteric obstruction (UUO) mouse model showed inhibition of renal fibrosis by preventing tubular epithelial cell death and neutrophil infiltration." (PMID 38900587, 2024).
Stroke (3 papers, 2014 to 2026). Sudden impairment of blood flow to a part of the brain due to occlusion or rupture of an artery to the brain. "While stroke, inflammation, and hypoxia are known to broadly affect transcriptional activity, we found no specific reports indicating that PPIB or POLR2A are directly regulated under these conditions in the human brain." (PMID 41602576, 2026).
abscess (2 papers, 2019 to 2023). An inflammatory process characterized by the accumulation of pus within a newly formed tissue cavity which is the result of a bacterial, fungal, or parasitic infection or the presence of a foreign body. "Using murine abscess and systemic models of infection, we show that a ppiB mutant in a USA300 background is attenuated for virulence but that a prsA mutant is not." (PMID 31208155, 2019).
fibrosis (2 papers, 2019 to 2024). the formation of excess fibrous connective tissue in an organ or tissue in a reparative or reactive process. "We applied PAL and chemical proteomics to connect PPIB, an ER-resident chaperone involved in collagen type I folding and maturation, as a mechanistic target for SfA in fibrosis." (PMID 38900587, 2024). "Incorporation of compounds acting through PPIB into the currently paltry arsenal of antifibrotic therapeutics has the potential to usher in an era of improved outcomes for patients suffering from fibrosis." (PMID 38900587, 2024). "Comparison of SfA and SfA-mc, which similarly inhibit and induce PPIB secretion, indicates that targeting PPIB may be separable from the immunosuppressive effects of SfA, and further structure-activity relationship studies may yield optimized molecules for treatment of fibrosis." (PMID 38900587, 2024).
head and neck cancer (2 papers, 2022 to 2025). A primary or metastatic malignant neoplasm affecting the head and neck. "PPIB was a cyclosporine-binding protein that participated to regulate cyclosporine A-mediated immunosuppression, further investigation revealed PPIB conferred radiation resistance in head and neck cancer via facilitating DNA repair." (PMID 35280744, 2022).
malignant glioma (2 papers, 2018 to 2024). A grade III or grade IV glioma arising from the central nervous system. "PPIB encodes cyclophilin B (CypB), which is an essential survival signal in the GBM cells expressed in many cases of malignant glioma." (PMID 38256047, 2024).
osteoarthritis (2 papers, 2019 to 2022). A noninflammatory degenerative joint disease occurring chiefly in older persons, characterized by degeneration of the articular cartilage, hypertrophy of bone at the margins and changes in the synovial membrane. "This analysis, and subsequent experimental confirmation, revealed five novel osteoarthritis-associated proteins (PPIB, ASS1, LHDB, TPI1, and ARPC4-TTLL3)." (PMID 35457215, 2022).
osteogenesis imperfecta type 9 (2 papers, 2014 to 2019). Any osteogenesis imperfecta in which the cause of the disease is a mutation in the PPIB gene. "Mutations in PPIB cause recessively inherited osteogenesis imperfecta type IX, a moderately severe to lethal bone dysplasia." (PMID 24968150, 2014).
giardiasis (1 paper, 2021). An infection of the small intestine caused by the flagellated protozoan giardia lamblia. "Yet, the detailed role of PPIB in giardiasis remains to be explored." (PMID 34943932, 2021).
glomerular disease (1 paper, 2022). "In a glomerular disease microarray dataset, PPIB was the most stable gene." (PMID 35593050, 2022).
growth deficiency (1 paper, 2014). "The resulting murine phenotype reproduces the clinical findings in patients with PPIB deficiency, including growth deficiency with bone deformities, reduced bone mineral density, decreased bone volume and strength." (PMID 24968150, 2014).
head and neck squamous cell carcinoma (1 paper, 2019). A squamous cell carcinoma that arises from any of the following anatomic sites: lip and oral cavity, nasal cavity, paranasal sinuses, pharynx, larynx, and salivary glands. "Paul reported that PPIB expression was associated with radioresistance in head-and-neck squamous cell carcinoma, affecting outcomes after radiotherapy." (PMID 31040200, 2019).
lung fibrosis (1 paper, 2024). "Taken together, our in vivo data support that SfA modulates PPIB, which is a therapeutic target for the treatment of skin and lung fibrosis." (PMID 38900587, 2024). "In summary, our work shows that the natural product SfA exerts antifibrotic effects by targeting PPIB, interfering with collagen maturation, and reversing bleomycin-induced skin and lung fibrosis in a mouse model." (PMID 38900587, 2024).
Machado-Joseph disease (1 paper, 2020). "PPIB is believed as the optimal reference gene in analyzing the blood of Machado-Joseph disease (MJD) patients." (PMID 33003996, 2020).
periodontitis (1 paper, 2017). An acute or chronic inflammatory process that affects the tissues that surround and support the teeth. "PPIB and TBP are most stably expressed in hPDL fibroblasts stimulated with Agac toxins and should therefore be used for in vitro experiments on periodontitis." (PMID 29116140, 2017).
sarcopenia (1 paper, 2022). Progressive decline in muscle mass due to aging which results in decreased functional capacity of muscles. "In this study, we newly identified a number of progeroid phenotypes in PpiB knockout mice, including abnormal teeth, reduced adiposity, and sarcopenia." (PMID 36248275, 2022).